LINC00900 (long independently transcribed non-coding RNA 900)
Gene: Long non-coding RNA gene on chromosome 11 (115,751,762 to 115,761,492, reverse strand). Ensembl gene ENSG00000246100.
Diseases named in the same sentence as LINC00900 in open-access papers:
LINC00900 is named in the same sentence as 3 diseases in open-access papers, as found by Europe PMC text mining. Sharing a sentence is not in itself a finding about the gene and the disease. The quoted sentences say what the papers report.
glioma (1 paper, 2021). A benign or malignant brain and spinal cord tumor that arises from glial cells (astrocytes, oligodendrocytes, ependymal cells). "A nine-EMT-related lncRNAs (HAR1A, LINC00641, LINC00900, MIR210HG, MIR22HG, PVT1, SLC25A21-AS1, SNAI3-AS1, and SNHG18) signature was identified in patients with glioma." (PMID 34288803, 2021). "Among the nine EMT-related lncRNAs identified in this study, LINC00900, MIR210HG, MIR22HG, PVT1, and SNHG18 were positively correlated with glioma malignancy, whereas HAR1A, LINC00641, SLC25A21-AS1, and SNAI3-AS1 were negatively correlated with glioma malignancy." (PMID 34288803, 2021).
tumor (2 papers, 2021 to 2022). "LINC00900, MIR210HG, MIR22HG, PVT1, and SNHG18 expression increased, whereas HAR1A, LINC00641, SLC25A21-AS1, and SNAI3-AS1 expression decreased with tumor grade." (PMID 34288803, 2021).
cancer (1 paper, 2022). A tumor composed of atypical neoplastic, often pleomorphic cells that invade other tissues. "In our research, a few of the DEirlncRNAs in the model have already been revealed to play roles in various cancers, such as HAGLROS, LBX2-AS1, LINC00900, LINC01614, AC090673.1, and especially TC, while others were found to be related to TC for the first time." (PMID 35996170, 2022).